TNF (tumor necrosis factor)
Diseases named in the same sentence as TNF in open-access papers (continued):
Sharing a sentence is not in itself a finding about the gene and the disease.
Obesity (continued). "Our main objective was to evaluate the levels of adiponectin, leptin, TNFα, IL6, and IGFs 1 and 2 in endometrial cancer patients compared to control patients with benign gynaecological conditions and to assess their relationship with obesity using the WHO BMI classification." (PMID 38339282, 2024). "In contrast, recent research found that IL-6 was not but TNF alpha was affected by a walking exercise; however, the participants were postmenopausal women with obesity (68–72 years old), and this might have affected the study outcomes." (PMID 39199416, 2024). "Obesity is also known to be accompanied by low-grade chronic inflammation showing increased proinflammatory chemokines and cytokines, such as monocyte chemotactic protein-1 (MCP1), interleukin-1β (IL-1β), interleukin-6 (IL-6) and tumor necrosis factor-α (TNF-α)." (PMID 38464534, 2024). "Indeed, it has been shown that obesity hampers the response to subcutaneous anti-TNF but not to ABA and TCZ." (PMID 38979406, 2024). "LCN2 participated in obesity and its metabolic complications such as T2DM, and cardiovascular diseases, which may relate to the activation of LCN2 signaling (such as TNF-α/NLRP3/LCN2) inducing mitochondrial dysfunction, oxidative stress, insulin resistance, and macrophage activation in adipocytes." (PMID 39609876, 2024). "The study was aimed to evaluate the secretion of inflammatory cytokine tumor necrosis factor-α (TNF-α) in the primary culture of monocytes, and to analyze its relationship with the number of mitochondrial DNA (mtDNA) copies in the blood of patients with coronary heart disease (CHD) and obesity." (PMID 38572445, 2024). "Obesity resulted in a marked increase in the expression of cyclooxygenase-2 (COX-2) and IL-6 in the adipose tissue of HFD animals, with concurrent moderate increases in TNF-α, IL-17A, and IL-18, while IL-1β changes were minor and inducible nitric oxide synthase (iNOS) expression was reduced." (PMID 38672413, 2024). "Additionally, TNF-α, an inflammatory cytokine involved in numerous pathological mechanisms, and soluble TNF-α receptors, might be important in explaining the obesity paradox." (PMID 38732147, 2024). "Leptin, adiponectin, resistin, visfatin, omentin, and inflammatory cytokines (such as tumor necrosis factor-alpha (TNF-α), interleukin-6 (IL-6), and monocyte chemoattractant protein-1 (MCP-1)) are just some of the known hormones that are released by adipocytes in both obesity and diabetes." (PMID 37441501, 2023). "A recent systemic review highlighted improvements in inflammatory biomarkers in adults with obesity using aerobic exercise training (decreased CRP, IL-6, and TNF-α), resistance training (decreased TNF-α), and concurrent training including both aerobic and resistance training (decreased TNF-α)." (PMID 37372149, 2023). "Our results suggest that by attenuating the TNF-α-induced changes in inflammatory cytokines and chemokine MCP-1 and by reducing oxidative stress, the studied coffee metabolites may prevent adipose tissue unbalance and thus obesity-related complications." (PMID 38202671, 2023). "Additionally, data related to plasma cytokines confirm these increases in TNF-α and IL-6 in animals with obesity and without treatment." (PMID 37445834, 2023). "In addition, obesity, especially visceral obesity that is present in most patients with NAFLD, is known to be a state of subclinical chronic inflammation, which is characterized by elevated production and secretion of inflammatory cytokines, including TNF-α." (PMID 37958479, 2023). "Future studies with a larger sample size are warranted to decipher the exact crosstalk between CAV1 and TNF-α and the mechanism by which CAV1 plays an important role in transmitting signals from the cell surface via intracellular signaling pathways that regulate inflammation in obesity." (PMID 37048092, 2023).
Obesity (continued). "Insulin resistance induced by hyperglycemia and obesity also converges with inflammation and immune modulation in the insulin receptor substrate 1 (IRS-1)/mitogen-activated protein kinase (MAPK)/Akt/phosphatidylinositol-3 kinase (PI3K) and NF-κB/IL-1β/TNF-α/interferon-γ (IFN-γ) pathways." (PMID 37298118, 2023). "Besides, PQQ also could protect hepatocyte from lipotoxicity and inflammation followed obesity via down-regulating the level of pro-inflammatory cytokines (NLRP3, IL-6, TNF and IL-1β)." (PMID 37935689, 2023). "In the future, in vivo studies are required to confirm the anti-obesity effects of Car derivatives—especially CD3—and gain new insight into the mechanism by which CD3 reduces the adipogenesis of 3T2-L1 and WJ-MSCs preadipocytes and TNF-α-induced inflammation in THP-1 cells." (PMID 36986440, 2023). "A large body of evidence suggests that inflammatory cytokines such as TNF-α, IL-1β, and IL-6 not only induce systemic insulin resistance but also affect lipid metabolism, whereas the presence of IL-10 effectively improves insulin sensitivity and HFD-induced obesity." (PMID 38162665, 2023). "In summary, TNFα is an inflammatory cytokine produced by monocytes and macrophages, and it is involved in the development of insulin resistance by impairing insulin signaling in the WAT and muscles, with visceral fat obesity being a significant site of its production in individuals with obesity." (PMID 37755259, 2023). "Interestingly, the silencing of CIDEA stimulated lipolysis and increased TNF-alpha secretion, revealing a role of the factor in the regulation of lipolysis regulation and metabolic complications of obesity in humans, possibly mediated by cross-talk between CIDEA and TNF-alpha." (PMID 35630580, 2022). "The results on the survival rate and occurrence of severe proteinuria in this study suggest that obesity induced by HFD significantly reduced the therapeutic effect of methylprednisolone in SLE, in a process probably involving proinflammatory cytokines such as IL-6, MCP-1 and TNF-α, and adipokines." (PMID 36323742, 2022). "However, regarding the increase in IL-6, CRP, and TNF-α in adolescents with obesity, resistance training (RT) did not lead to significant differences." (PMID 36293806, 2022). "Among the secreted cytokines, TNF-α has been observed to produce changes in the transcription of different molecules, in particular the insulin receptor, IRS-1 and GLUT-4, altering the normal insulin signaling pathway, and treatments aimed at blocking TNF-α improve obesity-induced IR." (PMID 36364954, 2022). "A possible explanation may be the fact that TNFα is produced mainly by the adipose tissue in individuals with obesity, and there was no significant change in the percentage of body fat in this group despite the reduction in BMI." (PMID 35586621, 2022). "Similarly, it seems that smoking, obesity, and diabetes, which only slightly increase serum TNF-α concentration, do not have a significant influence on the results." (PMID 36005576, 2022). "Importantly, in endometrial cells under hyperandrogenic and hyperinsulinemic conditions, TNFα increases the inactive form of IRS1, suggesting that a PCOS environment induces different alterations of p-IRS1 compared with the obesity condition in this in vitro model." (PMID 35409282, 2022). "However, when following a very-low-calorie diet, patients with obesity had reduced TNFα levels even though not to the average level exhibited by lean controls." (PMID 35062740, 2022). "However, while it has been shown that certain proinflammatory cytokines such as TNFα and IL-1β induce hepatic IGF-1 resistance, the contribution of IL-6 signaling in obesity-induced inflammation to hepatic insulin and IGF-1 downstream signaling remains controversial." (PMID 35628414, 2022).
Obesity (continued). "By studying different media compositions, including media in which we add only one parameter (for instance cytokines such as interleukin-1 beta (IL)-1β and IL-6 and tumor necrosis factor-alpha (TNF-α)), we could be able to link each effect of obesity to one or more factors." (PMID 36278576, 2022). "Subgroup analysis showed that AT (SMD = 0.36, 95% CI = −0.11~0.82, p = 0.13), RT (SMD = −0.83, 95% CI = 0.08~1.58, p = 0.03), and AT + RT (SMD = 0.34, 95% CI = −0.39~0.60, p = 0.69) could not reduce the TNF-α level in adolescents with obesity." (PMID 36293806, 2022). "In parallel, there is increasing evidence that pro-inflammatory signals like TNF-α, IL-1β, and IL-6 represent important components of the thermogenic potential of BAT and may lead to their altered capacity for energy expenditure and glucose uptake in obesity." (PMID 35436959, 2022). "However, a meta-analysis of RCTs in patients with T2DM and overweight or obesity reported that vitamin D supplementation significantly decreased circulating CRP concentrations but did not affect TNF-α or IL-6 concentrations." (PMID 35893929, 2022). "Previous studies have shown beneficial effects of TRF to reduce inflammation in individuals with obesity or metabolic diseases, and we have shown that eTRF reduces inflammation in individuals without obesity, in the form of reductions in the plasma concentrations of TNF-α and IL-8." (PMID 35194047, 2022). "In addition, many hormones and cytokines altered with obesity may influence ADPKD progression, including increased levels of insulin, insulin-like growth factor 1 (IGF-1), leptin, TNF-α, and IL-6, as well as decreased adiponectin." (PMID 35350649, 2022). "It is recognised that the severity of PCOS may be aggravated with obesity, and it has been reported that women with PCOS present higher serum concentrations of TNF and C-reactive protein (CRP) as well as monocyte and lymphocyte circulating levels, with inflammatory infiltration in ovarian tissue." (PMID 36079796, 2022). "Interestingly, in a series of 110 psoriasis patients treated with anti-TNF therapy, the majority of non-responders were smokers, especially those with overweight/obesity or higher baseline PASI scores." (PMID 35646971, 2022). "Excess adipose tissues in obesity release nonesterified fatty acids (NEFAs), glycerol, adipokines, and pro-inflammatory cytokines (tumor necrosis factor-α) [TNF-α], interleukin [IL]-6, IL-1β), leading to insulin resistance (IR) and type 2 diabetes mellitus (T2DM)." (PMID 36157449, 2022). "In most rheumatic diseases, IFN-γ and TNF produced by circulating MAIT cells decrease, while IL-17 produced by MAIT cells increases in blood and tissues, suggesting that MAIT cell proinflammatory IL-17 is biased in rheumatology similar to that in obesity and chronic liver disease." (PMID 35317168, 2022). "Interestingly, the reduction in inflammatory cytokines following SIT in our group of men with overweight and obesity occurred despite having no changes in fat mass and having relatively low TNF‐a and IL‐6 at baseline." (PMID 35312183, 2022). "Using a fixed-effect model, the combined effect size SMD = 0.34, 95% CI = −0.03~0.65 (p = 0.03), indicating that training could not reduce the TNF-α in adolescents with obesity." (PMID 36293806, 2022). "Furthermore, children with obesity with NAFLD had higher BMI, Fins, HOMA-IR, TG, ALT, AST, GGT, and TNF-α but lower HDL-C levels than children with obesity but without NAFLD." (PMID 33883996, 2021). "This is of importance since TNFα levels could be an important factor downregulating SHBG production during early stages of obesity development, but once children reach a certain point of inflammation, TNFα plasma levels may not influence SHBG production." (PMID 33689083, 2021).
Obesity (continued). "Moreover, adipose tissues secret a number of other cytokines, including interleukin-6 (IL-6), tumor necrosis factor α (TNFα), and monocyte-chemoattractant protein-1 (MCP-1), which may also contribute to obesity-promoted cancer initiation and progression." (PMID 33535537, 2021). "Moreover, bulk RNA-Seq revealed an enhanced transcriptional response to LPS at T3 relative to T1 in the lean subjects relative to those with obesity marked by higher expression of pro-inflammatory molecules (IL6, IL1B, TNF) and induction of transcription factors (RELA, IRF1, STAT3)." (PMID 34195568, 2021). "In response to CD3/CD28 stimulation, the secretion of TNF-α by CD8+ T cells trended towards positive correlation with BMI while IFN-γ secretion by CD8+ T cells significantly negatively correlated with BMI in young patients, suggesting an impairment of CD8+ T cells antiviral with obesity." (PMID 34707619, 2021). "In patients with obesity, overproduction of cytokines evokes a preexisting chronic inflammation, since adipocytes secretion of pro-inflammatory molecules (e.g. MCP-1, IL-6, IL-18, TNF-α, IL-1β) together with a decrease of anti-inflammatory cytokines (e.g. IL-10) has been reported." (PMID 34038475, 2021). "Our data do not support a link of inflammation (as determined by TNFα, IL‐6, procalcitonin and CRP values) to BCAA concentrations, thus the mechanisms underlying increased BCAA levels in obesity remain unclear." (PMID 33058486, 2021). "Hence, expanded adipocyte mass, overexpression of TNF-α and IL-6 mRNA and protein along with declined expression of PPAR-γ in adipocytes of HFD and sucrose fed rats clearly indicates the development of obesity induced inflammation and thus insulin resistance in them." (PMID 33917607, 2021). "Interestingly, GM-CSF, TNFα, and IL-12 (p70) were not produced in the early stages of obesity development." (PMID 34439950, 2021). "Obesity-related metabolic disorders elicit systemic low-grade inflammation by increasing the levels of proinflammatory factors, such as monocyte chemoattractant protein-1 (MCP-1), CD11c, tumor necrosis factor-α (TNF-α), leptin, lipopolysaccharide binding protein (LBP), and interleukin-6 (IL-6)." (PMID 34579036, 2021). "Moreover, the TNF-α-308A allele was associated with a decreased risk for EDS (odds ratio 0.64, 95% confidence interval 0.41–0.99; p = 0.043) independent of age, sex, obesity, OSA severity and the circulating TNF-α levels." (PMID 34362196, 2021). "However, inflammation status as a potentially important link between obesity and FLD and the specific mediation role or effect of key inflammatory biomarkers (hs-CRP, TNF-α and APN) between the association of obesity and FLD have not been explored." (PMID 34571772, 2021). "Interestingly, evidence shows that an increase in plasma LDL-CER in T2DM and the prevalence of obesity correlate with the severity of insulin resistance and elevated plasma TNF-α levels but not with the degree of obesity." (PMID 34940565, 2021). "Furthermore, since adipocytes release proinflammatory markers (TNF-a, IL-6, and CRP), obesity may dysregulate the inflammatory markers and potentiate the inflammatory response, which could lead to higher pain sensitivity." (PMID 34257764, 2021). "Visceral adipose tissue (VAT) produces higher inflammatory cytokines (TNF-α, IL-6, and IL-1β) in comparison to subcutaneous adipose tissue, suggesting that cytokine storm in COVID-19 infection could be independent of obesity." (PMID 34220807, 2021). "One possible mechanism for such increased haptoglobin production in obesity is a TNFα-mediated induction, since mice overexpressing TNFα present higher levels of haptoglobin and obese mice lacking this cytokine in white adipose tissue (WAT) resulted in a downregulation of adipose haptoglobin." (PMID 32752277, 2020).
Obesity (continued). "Interestingly, Biocarta also found significant overrepresentation in two well-known anti-inflammatory pathways: the PPARγ-related obesity pathway (Systemic name M22017) and the IL-10/JAK/STAT signaling pathway that result in the repression of TNFα, IL-1, and IL-6 (Systemic name M6778)." (PMID 33256749, 2020). "Our results indicates that in non-obese, apparently healthy women GG homozygosity of the G-308A TNF-α polymorphism is associated with enhanced low grade inflammation assessed by serum CRP-hs concentrations, and occurrence of obesity does not affect significantly CRP-hs levels in GG homozygotes." (PMID 30900134, 2020). "However, we noted no statistically significant change in the serum levels of TNF-α in class I obesity." (PMID 32893859, 2020). "During obesity-induced liver inflammation, hypertrophic adipocytes secrete free fatty acid, while several immune cells (including Kupffer cells and hepatic stellate cells (HSC)) produce pro-inflammatory cytokines (TNF-α, IL-6, IL-1β and IL-10) and adipokines (leptin and adiponectin)." (PMID 32948162, 2020). "Unlike TNF-α, IL-6 principally secreted in an endocrine (systemic) fashion and the expanding AT in obesity may contribute high levels of IL-6 in the circulation." (PMID 32893859, 2020). "To identify the set of potential intestinal bacteria contributing to obesity or to obesity with metabolic complications, namely, IR, we established correlations between abundances of selected OTUs and fecal immune markers that discriminate among the study groups, including MCP-1, IFN-γ, or TNF-α." (PMID 32209719, 2020). "In an HFD model of obesity in Swiss mice, the administration of CGS21680, an A2aAR agonist, improved glucose homeostasis, as determined by insulin tolerance test, and reduced inflammatory markers such as tumor necrosis factor alpha (TNFα) systemically and in the visceral adipose tissue." (PMID 33050467, 2020). "Given that FAM19A5 is expressed in human adipocytes and its mRNA expression and protein synthesis are downregulated by TNF-α, it has been hypothesized that the production of FAM19A5 may be conditioned by cardio-metabolic disorders related to obesity in humans." (PMID 33192583, 2020). "In addition, proinflammatory cytokines TNF-α and IL-1β transcript expressions were also detected in the monocytes and macrophages in the mouse adipose tissue SVF, which were well correlated with the reported proinflammatory function of FAS in obesity." (PMID 33488632, 2020). "One of the main factors contributing to the development of obesity is the consumption of a high-fat diet (HFD), characterized by high leptin levels in humans, mice and zebrafish (Danio rerio) and increase in tumor necrosis factor α (TNF-α) and interleukin 6 (IL-6) levels." (PMID 32635261, 2020). "However, phloretin did not suppress TNF-α gene expression in inguinal adipose of mice with HFD-induced obesity." (PMID 33014333, 2020). "Negative impact of TNF-α on insulin sensitivity in obesity has been reported decades ago." (PMID 32477009, 2020). "For instance, obesity tends to be accompanied by excessive consumption of HFD, and related to a chronic inflammation condition characterized by the increased plasma levels of proinflammatory cytokines such as tumor necrosis factor α (TNF-α), interleukin-6 (IL-6), and interleukin-1 (IL-1)." (PMID 31993071, 2020). "Chronic inflammation happens through frequent stress factors such as poor diet and obesity and it is recognized with high levels of serum inflammatory biomarkers including high sensitivity C-reactive protein (hs-CRP), interleukin (IL)-6, and tumor necrosis factor-α (TNF-α)." (PMID 33117453, 2020). "In summary, our results show that cooperative effect of stearic acid on the TNF-α induced production of MIP-1α/CCL3 depends on TLR4-TRIF-TBK1-IRF3 signaling cascade which suggests an interesting pathophysiological link among stearic acid, TNF-α, and MIP-1α/CCL3 in the state of obesity." (PMID 33050324, 2020).